Y_RNA (Y RNA )
Gene: Miscellaneous RNA gene on chromosome 3 (110,727,021 to 110,727,121, forward strand). Ensembl gene ENSG00000201426.
Homologues: Orthologues: chimpanzee Y_RNA (99% identical), macaque Y_RNA (95% identical), pig Y_RNA (72% identical). Paralogues in human: Y_RNA (86% identical), Y_RNA (85% identical), Y_RNA (84% identical), RNY3 (83% identical), RNY3P1 (83% identical), RNY3P16 (83% identical), Y_RNA (83% identical), Y_RNA (82% identical), Y_RNA (81% identical), RNY3P11 (80% identical), Y_RNA (80% identical), RNY3P14 (79% identical), and 92 more.